EGFR (epidermal growth factor receptor)
Diseases named in the same sentence as EGFR in open-access papers (continued):
Sharing a sentence is not in itself a finding about the gene and the disease.
tumor (continued). "ALL these finding supported that CSCLC is a collision tumor and it was unsuitable for TKI therapy despite the presence of EGFR mutations." (PMID 27145273, 2016). "All these results indicated that the TAZ-promoted proliferation and tumor formation of GBM cells were possibly mediated by potentiating the EGFR signaling pathway." (PMID 27167112, 2016). "We isolated patient-derived tumor cells (PDCs) from a rare MIBC case (BD-138T) that harbors concomitant epidermal growth factor receptor (EGFR) amplification and phosphatase and tensin homolog (PTEN) deletion." (PMID 27438149, 2016). "To validate this system, we first imaged tumor xenografts that were stained with an equimolar mixture of EGFR-NPs and isotype-NPs." (PMID 26878888, 2016). "Inhibition of EGFR via the small molecule inhibitors erlotinib and gefitinib commonly results in tumor resistance, even in patients with EGFR-mutant tumors that initially show substantial clinical responses." (PMID 27248176, 2016). "As a conclusion so far, curative effect of nimotuzumab is proportional to the tumor surface EGFR density of patients, and the low adverse events rate allows patients who received nimotuzumab plus irinotecan to gain a well quality of life." (PMID 26880889, 2016). "In accordance with our in vitro data, IL1A, IL1B and IL8 were overexpressed in tumorgrafts that proved to be resistant to EGFR blockade (tumor volume increase of at least 35% compared to the initial, pre-treatment volume)." (PMID 27708224, 2016). "We mainly used TE-11R cells to assess the cytotoxic or anti-tumour effect of EGFR(2R)-lytic hybrid peptide, because TE-11R cells are highly transformed cells with tumourigenicity." (PMID 26956916, 2016). "Further, we tested the expression of CD97-related factors (membrane receptors): CD55 (a CD97 ligand), CD44v6 (a cancer stem cell marker), and two potential tumor therapeutic markers, EGFR and HER2." (PMID 26233326, 2016). "Our study using a murine model for GBM driven by a single genetic driver, suggests differences in EGFR activation contribute to tumor heterogeneity and aggressiveness." (PMID 27738329, 2016). "Three additional groups of tumor samples were selected from normally expressed samples for both EGFR, MET and CDK6." (PMID 27329726, 2016). "The monoclonal antibodies cetuximab and panitumumab are directed against EGFR, therefore inhibiting cell proliferation and tumor growth, by binding to the extracellular domain of EGFR and blocking ligand-induced receptor phosphorylation and further signaling." (PMID 27563673, 2016). "The myriad of manners in which EGFR signaling regulates tumor cell response to treatments, combined with erlotinib being readily available in the clinic, substantiates its continued relevance as a promising therapeutic option." (PMID 27685624, 2016). "A permanent activation of the EGFR TK affects signaling in the RAS-RAF-MAP, as well as in the PIK3-AKT-mTOR, pathway associated with proliferation, invasion, metastatic spread, and tumor angiogenesis." (PMID 26784235, 2016). "AREG activates signalling in an autocrine manner in tumour cells, but it is also able to activate EGFR via paracrine signals from non‐resident cells of the microenvironment." (PMID 27196940, 2016). "EGFR is overexpressed in many tumours of epithelial origin including HNSCC showing upregulated expression in about 90% of patients." (PMID 27643613, 2016). "Negative (−) or weakly positive staining (+/−) was observed in 36/49, 18/49, 29/49, and 15/49 of the tumor samples for Tid1-L, EGFR, hnRNP A1, and hnRNP A2, respectively." (PMID 26919236, 2016). "Once again, IHC analysis performed in pretreatment tumor biopsies from HNSCC patients revealed a beneficial role of high EGFR expression in patients assigned to continuous hyperfractionated accelerated RT compared with conventionally-fractionated RT." (PMID 27556186, 2016).
tumor (continued). "The detection of tumours in an early phase of tumour development in combination with the knowledge of expression of tumour markers such as epidermal growth factor receptor (EGFR) is an important prerequisite for clinical decisions." (PMID 26912069, 2016). "As measured by FDG-PET, and visualized by MRI, early tumor-imaging response has proven concordant with impeded EGFR downstream signaling and histopathological assessment." (PMID 27494838, 2016). "The presence of EGFR-vIII makes tumor cells more sensitive to EGFR tyrosine kinase inhibitors (TKIs)." (PMID 26755558, 2016). "In an exploratory study of 40 patients with EGFR mutation-positive tumors progressing on EGFR TKI therapy, the T790M genotype from tumor biopsies was compared with findings from simultaneously collected circulating tumor cells and circulating tumor DNA." (PMID 26970967, 2016). "This observed anti-tumor effect was more pronounced with the miRNAs than with targeted silencing of the EGFR and PIK3CA proteins using validated siRNAs." (PMID 27095166, 2016). "Levitzki used chemical vectors attached to a specific ligand, such as antibody against EGFR in tumor cells, to introduce poly(I:C) into tumor cells." (PMID 27336891, 2016). "It is suggested that TGFα pathway and the autocrine activation of EGFR, leading to tumor growth, apoptosis inhibition and metastasis play a role in this process." (PMID 27055285, 2016). "TKIs competitively antagonize the binding of ATP to a TKD, which thus inhibits the autophosphorylation of receptor tyrosine kinases and blocks the activation of EGFR-mediated signaling pathways, ultimately leading to the inhibition of tumor cell proliferation." (PMID 26728266, 2016). "It is well known that EGFR modulates several steps of cancer progression and one of the first steps is adhesion of cancer cells to the non‐tumour cells in the microenvironment." (PMID 27196940, 2016). "Further, we were able to show that EGFR inhibition can indeed enhance antigen specific T cell mediated tumor killing." (PMID 27467256, 2016). "As was reported, the dual vascular endothelial growth factor receptor (VEGFR) and EGFR blockade inhibit tumor growth in EGFR TKI resistance xenograft models." (PMID 28149837, 2016). "One tumor exhibited a high level of FGFR2 amplification with a low level of EGFR and KRAS amplification." (PMID 27014419, 2016). "Internalization of EGFR/ligand (EGF or anti-EGFR antibodies) is a physiological mechanism affecting the tumor cell response to growth and inhibition stimuli." (PMID 26575422, 2016). "In the studies reported here, we evaluated fluence rate effect on EGFR activation in tumor nodules of the PDT-treated murine thoracic cavity." (PMID 26784170, 2016). "Expression of COX-2 and EGFR has been demonstrated to have an important role in tumor angiogenesis in many cancers." (PMID 26881213, 2016). "It is now accepted that in stage IV colorectal disease, RAS mutations confer resistance to anti‐EGFR therapy and BRAF mutations are an indicator of poor prognosis; however, even among patients with RAS WT tumours, only a minority respond." (PMID 26690310, 2016). "Several studies have been reported regarding immune responses to tumor-specific EGFR mutations, such as EGFRvIII in GBM and EGFR T790M in NSCLC." (PMID 27833557, 2016). "In summary, the serial assessment of EGFR mutations in the plasma of NSCLC patients allows conclusions about controlled disease and tumor progression earlier than currently available methods." (PMID 27640882, 2016). "Tumour expression of the biomarker amphiregulin (AREG) has also been correlated with survival during anti-EGFR therapy." (PMID 27764839, 2016). "On EGFR overexpressed tumor cells experiments in vitro, nimotuzumab showed remarkable cancer reversing effects such as antiproliferation, antiangiogenesis and promotes apoptosis." (PMID 26880889, 2016).
tumor (continued). "This shows that somatic events in EGFR are common and complex and that studies of tumor heterogeneity assumes that it also is an early event as it was evident in all parts of the tumor." (PMID 26906551, 2016). "Our study uncovers the role of a novel alternative tumor suppressor miRNA gene- miR-3622b- in this region that plays a crucial role in PCa by regulating EGFR." (PMID 27611943, 2016). "As we have discussed here, PI3K/Akt/mTOR signal pathway after activation of EGFR is one of the most significant signal pathways in tumor cells." (PMID 26967052, 2016). "EGFR is highly expressed in a variety of human tumors, including NSCLC, and is implicated in tumor development and progression." (PMID 26824318, 2016). "Angiogenesis also plays a crucial role in tumor malignancy and progression, and various angiogenesis-related genes and pathways, especially the EGFR/IGFBP2/HIF2αpathway, are upregulated in pHGGs." (PMID 26933822, 2016). "New emerging evidence suggests that the anti-tumor activity of EGFR-TKIs in resistant NSCLC cell lines can be enhanced by combined therapy with other regimens." (PMID 27098372, 2016). "Nude mice bearing subcutaneous U87MG.∆EGFR xenografts were treated with nimotuzumab and/or TMZ, and were sacrificed after the first week of treatment (6 days after the start of treatment) to prepare tumor lysates to examine EGFR status of the tumor cells." (PMID 26778701, 2016). "In this study we demonstrate that the use of anti-EGFR nanobody 99mTc-D10 is especially suitable to detect small tumour lesions expressing EGFR with high specificity and high contrast 45 min after administration." (PMID 26912069, 2016). "The proportion of micropapillary element was higher in the EGFR-mutated LADC at the advanced stage (stage II, III, or IV) than in the tumor at the early stage (stage I) (Mann-Whitney test, P<0.0001)." (PMID 27861549, 2016). "The imaging responses correlated with the inhibition of downstream EGFR signaling, increased apoptosis, and decreased proliferation in the tumor tissues." (PMID 27494838, 2016). "Since high mannose EGFR has reported to represent a novel tumor-specific antigen, PFL would be useful as a cancer targeting material." (PMID 26850110, 2016). "Tumor cell biological research has mostly focused on the druggable kinases, and many tyrosine kinase genes are listed as proto-oncogenes (e.g. EGFR, MET, ERBB2, and PDGFRA)." (PMID 27586084, 2016). "CellProfiler was used to calculate the proportion of each tumor with MUC1 expression, EGFR expression, MUC1/EGFR co-expression as well as the intensity of associated staining." (PMID 27092881, 2016). "Studies have indicated that EGFR mutations and possibly other abnormalities of EGFR leading to enhanced SRC expression are important determinants of tumor sensitivity to SRC kinase inhibitors." (PMID 27438149, 2016). "Traditionally, the common outcomes of the EGFR-mediated signaling in cancer cells are uncontrolled tumor proliferation and enhanced survival of the tumor cells." (PMID 30370422, 2016). "The epidermal growth factor receptor (EGFR) is known to contribute to cell survival signals as well as metastatic potential of some tumours." (PMID 26870997, 2016). "The comprehension of activity in T790M-negative tumours and mechanisms of resistance to third-generation EGFR TKIs are warranted for future investigations." (PMID 27433281, 2016). "Many known tumor targets such as EGFR, HER2, CD105, VEGFR, and folate receptors have been tested for fluorescence visualization of tumors." (PMID 27800481, 2016).
tumor (continued). "To further investigate the role of EGFR in miR‐134‐mediated tumour suppression, we conducted RNAi and functional rescue experiments, which confirmed that down‐regulation of EGFR by miR‐134 partially contributes to the proliferation suppressive role of miR‐134." (PMID 27241841, 2016). "It appears advisable to estimate EGFR protein by a IHC method considering both intensity and extent of the staining, as well as stratifying patients by specific tumor sites." (PMID 27556186, 2016). "In circulating cell-free tumour DNA of patients treated with anti-EGFR antibodies, RAS mutations emerge earlier than EGFR ECD variants." (PMID 27929064, 2016). "For these individuals, however, disease progressed; this is indicated by either tumour re-growth (Patient 2) or brain metastasis (Patient 8) despite continued EGFR TKI treatment." (PMID 27325363, 2016). "A431 tumours (EGFR++/CD44v6++) and UM-SCC-74B tumours (EGFR+/CD44v6+) contained viable tumour and stromal cells, well-established blood vessels and minor areas of necrosis." (PMID 26627081, 2016). "Combination studies of immune checkpoint inhibitors with cytotoxic chemotherapy or with molecularly targeted agents, such as inhibitors of the epidermal growth factor receptor or angiogenesis, are actively being conducted in different types of tumours." (PMID 26927178, 2016). "Subsequently, several anti-EGFR aptamers were generated and their tumor-suppressive functions have been demonstrated in a variety of cancers." (PMID 26863567, 2016). "It is assumed, that targeting of the EGFR improves tumor control at least in part by increasing the cellular radiosensitivity of the tumor cells." (PMID 27281611, 2016). "Multivariate Cox regression analysis revealed that tumor stage IV, wild-type EGFR status and NLR ≥ 3.7 were independent prognostic factors for worse PFS." (PMID 27029035, 2016). "Surface EGFR expression was observed not only on tumor cells from the primary lesions, but also on those from the brain metastases (bottom two rows)." (PMID 27050072, 2016). "Erlotinib is an EGFR-targeted drug that inhibits tumor growth by suppressing EGFR and its downstream signal pathways." (PMID 26636541, 2016). "EGFR activation is related to the stimulation of tumor angiogenesis, which is essential to growth, proliferation, and metastasis of cancer cells." (PMID 27362942, 2016). "We functionally validated the therapeutic efficacy of PD-1 blockade in this mouse model and showed that suppression of EGFR signalling decreased PD-L1 expression on tumour cells." (PMID 26883990, 2016). "Evidences suggest a role of IGF-1R in the progression of tumor and a functional cross talk between EGFR and IGF-1R." (PMID 27895663, 2016). "Several tumour-promoting biomarkers such as EGFR, IGF1R, IR and c-Met are also co-overexpressed in TNBC." (PMID 27502396, 2016). "Our results demonstrate that IL-17E, in addition to its involvement in tumor progression, contributes to EGFR resistance." (PMID 27462789, 2016). "In this study, we sought to investigate immediate-early effects of EGFR TKI treatment on tumor regression and tumor microenvironment in mutant EGFR-driven “pre-clinical” genetically engineered mouse (GEM) models." (PMID 27494838, 2016). "To test the ability of 25D3 to suppress EGFR mutant xenograft growth, we implanted tumor cells in mice that were pre-fed diets containing variable levels of VD3." (PMID 26654942, 2016). "In summary, we demonstrate that ABT-869 and chemotherapies act synergistically to inhibit the tumor growth and angiogenesis in vitro and in vivo through simultaneous blockade of EGFR-, IGF1R- and VEGR2-mediated AKT/mTOR signaling pathways." (PMID 27387652, 2016). "These include platelet-activating factor receptor (PAFR) that causes platelet mobilisation and promotes tumour metastases, as well as epidermal growth factor receptor (EGFR) which also promotes tumour invasion." (PMID 27566553, 2016).
tumor (continued). "Considering that EGFR ECD mutations completely abrogate the interaction with anti-EGFR monoclonal antibodies, it is unclear why only a fraction of relapsed tumours display these alterations." (PMID 27929064, 2016). "The early change in PM score can be considered to reflect early tumor responses to EGFR-TKI treatments, and hence should show good correlation to changes in chest X-p but not in CT." (PMID 27708242, 2016). "In this regards, EGFRvIII is particularly interesting as the deletion in the extracellular domain creates a tumor‐specific epitope that can be used as a target for anti‐EGFR antibodies for targeting the fastest proliferating cells." (PMID 26778701, 2016). "Since antibodies elicited by Hsc70-P19 and Hsc70-P26 were able to bind to EGFR, we assessed the growth inhibiting effects of these antibodies on tumor cells expressing high levels of EGFR by MTT and colony formation assays." (PMID 27659529, 2016). "Conversely, an additional body of evidence has connected EGFR (ErbB1)-targeted treatments with the stimulation of autophagy, thereby helping tumor cells’ death escape." (PMID 27486382, 2016). "Taken together, these results emphasize the clinical importance of intra-patient tumour heterogeneity arising during EGFR-targeted therapy for NSCLC." (PMID 27283993, 2016). "Our tumor marker profiling informed a therapeutic strategy for co-targeting the EGFR and PTEN/PI3K nodes." (PMID 27484095, 2016). ""Patients with EGFR or ALK genomic tumor aberrations should have disease progression on FDA-approved therapy for these aberrations prior to receiving nivolumab," said Ms." (PMID 29152394, 2016). "These inhibitors not only prevent the autophosphorylation and activation of these receptors in tumor cells but also bind to EGFR or HER-2 dimers to inhibit downstream signaling pathways." (PMID 26728266, 2016). "On the contrary, the entire tumor is a mixture of heterogeneous cancer cell clones with varying sensitivity to EGFR-TKIs." (PMID 27708242, 2016). "Systematic preclinical investigation of anti-EGFR signaling agents in human tumor cells and animal model systems has proven valuable in the logical design of clinical trials testing EGFR inhibitors." (PMID 27716204, 2016). "Conversion of protein expression between primary tumour and metastatic lymph nodes was seen in 8 cases (6 from low to high, 2 from high to low) for EGFR and in 4 cases (all low to high) for HER3." (PMID 26844548, 2016). "The MP and glomerulus-like portions in AC tumours exhibited a congenial EGFR status, but the acinar cells with papillary cells were heterogeneous." (PMID 27046167, 2016). "Gene mutations in the genes encoding EGFR, FGFR2, KDR, and RET were discovered in the patient's tumor tissue by whole exome sequencing and the patient was treated with a combination of the targeted drugs cetuximab and sunitinib." (PMID 27149458, 2016). "Hypoxia selective inhibition of EGFR was demonstrated in vitro, and anticancer activity in vivo against A431 and Calu3 human tumour xenografts was demonstrated." (PMID 26811177, 2016). "Pre-clinical studies using EGFRL858R/T790M-driven tumor models have shown that afatinib-cetuximab combination treatment can achieve significant tumor regression, a finding further confirmed in patients with acquired resistance to EGFR TKIs." (PMID 27494838, 2016). "In NSCLC xenografts, Imprime enhanced the anti-tumor efficacy of the anti-EGFR tumor-targeting antibody, cetuximab." (PMID 27812183, 2016). "In our study, we found that miR‐133a suppressed cell proliferation and tumor size, and increased the survival rate more significantly, compared with EGFR siRNA." (PMID 27465833, 2016). "These include gain-of-function mutations in EGFR, K-RAS, BRAF, and EML4-ALK, all signifying the importance of the MAPK pathway for this tumour type." (PMID 27350784, 2016). "In antral/pyloric tumours, the observed prevalence of EGFR gene amplification was intermediate to that in other locations." (PMID 27387915, 2016).